KIF4A (kinesin family member 4A)
Description:
Iron-sulfur (Fe-S) cluster binding motor protein that has a role in chromosome segregation during mitosis. Translocates PRC1 to the plus ends of interdigitating spindle microtubules during the metaphase to anaphase transition, an essential step for the formation of an organized central spindle midzone and midbody and for successful cytokinesis. May play a role in mitotic chromosomal positioning and bipolar spindle stabilization (By similarity).
Synonyms: KIF4; KIF4-G1; HSA271784; FLJ12530; FLJ12655; FLJ14204; FLJ20631; MRX100; KIF4G1; TMDI; XLID100
Tractability: PROTAC: UniProt records ubiquitination sites on it; ubiquitination databases record sites on it.
Target class: Enzyme; Hydrolase
Gene: Protein-coding gene on chromosome X (70,290,067 to 70,420,886, forward strand). Ensembl gene ENSG00000090889.
Subcellular location: Nucleus matrix; Cytoplasm; Cytoplasm, cytoskeleton, spindle; Midbody; Chromosome
Subcellular location (Human Protein Atlas): Midbody; Nucleoplasm; Acrosome; Equatorial segment; Mid piece; Principal piece
Pathways (Reactome):
Developmental Biology: Recycling pathway of L1
Hemostasis: Kinesins
Immune System: MHC class II antigen presentation
Vesicle-mediated transport: COPI-dependent Golgi-to-ER retrograde traffic
Gene Ontology:
Molecular function: protein binding; microtubule motor activity; ATP binding; microtubule binding
Biological process: mitotic cytokinesis; mitotic spindle midzone assembly; anterograde axonal transport; mitotic spindle organization; organelle organization; spindle elongation; microtubule-based movement
Cellular component: chromosome; cytoplasm; membrane; midbody; nuclear matrix; cytosol; microtubule associated complex; spindle microtubule; axon cytoplasm; spindle
Gene-disease validity (ClinGen):
ClinGen rates the evidence that KIF4A causes each of these diseases.
complex neurodevelopmental disorder with or without congenital anomalies (X-linked): Limited. A complex neurodevelopmental disorder that involves more than one phenotype associated with the central nervous system, including but not limited to intellectual disability, autism, and seizures (epilepsy), in addition to one or more structural or functional anomaly(ies) that develops prenatally.
Homologues: Orthologues: chimpanzee KIF4A (100% identical), macaque KIF4A (99% identical), dog KIF4A (95% identical), pig KIF4A (94% identical), guinea pig KIF4A (92% identical), rabbit KIF4A (92% identical), mouse Kif4 (87% identical), rat Kif4a (87% identical), tropical clawed frog kif4a (70% identical), zebrafish kif4 (62% identical). Paralogues in human: KIF4B (94% identical), KIF21A (33% identical), KIF21B (32% identical), KIF27 (26% identical), CENPE (25% identical), KIF7 (24% identical), KIF15 (21% identical), KIF13B (20% identical), KIF13A (20% identical), KIF5A (20% identical), KIF16B (19% identical), KIF1A (19% identical), and 29 more.
Diseases named in the same sentence as KIF4A in open-access papers:
KIF4A is named in the same sentence as 89 diseases in open-access papers, as found by Europe PMC text mining. Sharing a sentence is not in itself a finding about the gene and the disease. The quoted sentences say what the papers report.
breast carcinoma (33 papers, 2017 to 2025). "Kinesins have been recently highlighted as prognostic biomarkers in breast cancer and a 6-KIFs-based risk score (including four MT-Rel genes, KIF4A, KIF15, KIF18B, KIF20A) was reported to accurately predict outcomes." (PMID 37835564, 2023). "The dys-regulation of KIF4A is associated with the outcome of several cancer types, including lung, cervical, oral, and breast cancer." (PMID 35028418, 2022). "And elevated levels of KIF4A are associated with poor survival of breast cancer and that knockdown of KIF4A strongly suppresses cell proliferation and induces apoptosis." (PMID 30744636, 2019). "In breast cancer, high KIF4A levels were associated with poor relapse-free survival of ER-positive patients." (PMID 30254986, 2018). "First, kinesin family member 4A (KIF4A) is a microtubule-based motor protein that has been reported to be associated with various cancers, such as oral squamous cell carcinoma, cervical cancer, breast cancer, prostate cancer, colorectal cancer, and lung cancer." (PMID 31987036, 2020). "miRNA Mimics: Developing nanomedicines that deliver miRNA mimics (e.g., miR-335, miR-379-5p) to restore their natural inhibition of KIF4A has the potential to reduce tumour growth by 35%-50% in models such as breast cancer." (PMID 41361459, 2025). "In breast cancer, silencing KIF4A diminishes Smad3 phosphorylation, alters TGF-β1/Smad3 pathway activity, and influences epithelial-mesenchymal transition (EMT) as well as immune factor expression." (PMID 41361459, 2025). "In breast cancer (BC), KIF4A is a prominent oncogenic driver, exhibiting significant upregulation that correlates with tumour malignancy and poor prognosis, demonstrating predictive power that surpasses traditional clinical indicators." (PMID 41361459, 2025). "Previous research has provided evidence for the oncogenic role of KIF4A in various types of human cancers, including hepatocellular carcinoma, cervical carcinoma, breast cancer, oral cancer, and colorectal cancer." (PMID 41462522, 2025). "In breast cancer, adriamycin can induce apoptosis in tumor cells by downregulating the expression of KIF4A." (PMID 38937742, 2024). "Consistently, circKIF4A showed greater stability of circular structure in the three different breast carcinoma cell lines than linear KIF4A mRNA." (PMID 36052282, 2022). "For example, Ispinesib, a KIF11 inhibitor, was evaluated in a phase I clinical trial in breast cancer, although the specific inhibitors for KIF4A and KIF18B are still limited." (PMID 36499051, 2022). "Further researches have shown that KIF4A operates as an oncogene and plays critical roles in a number of malignancies, including breast cancer, prostate cancer and colorectal cancer." (PMID 35646102, 2022). "For instance, circ_100876 accelerates breast cancer cell proliferation and metastasis through sponging miR-361-3p; circKIF4A functions as a ceRNA to accelerate the KIF4A expression by sponging miR-375, thus aggravating breast cancer." (PMID 34732216, 2021). "The expressions of KIF4A, RACGAP1, CKS2, SHCBP1, and HMMR were high in breast cancer, associated with poor OS and different breast cancer subclasses." (PMID 33959662, 2021). "KIF4A can tether Rap GTPase Interactor to microtubules, resulting in integrin activation and alteration in migration and invasion of breast cancer." (PMID 33995648, 2021). "PKMYT1, KIF4A, and CDC25C were associated with GO in terms of BPs; previous studies also revealed the overexpression of these genes in breast cancer." (PMID 34834441, 2021). "In hepatocellular carcinoma, breast cancer and prostate cancer, the up-regulation of KIF4A can predict poor prognosis." (PMID 31788359, 2019). "KIF4A (kinesin family member 4A) has been identified as an oncogene that is overexpressed in several malignancies including breast cancer." (PMID 30744636, 2019).
breast carcinoma (continued). "In tamoxifen-resistant and sensitive breast cancer cells, KIF4A knockdown significantly impeded cellular proliferation and induced apoptosis." (PMID 30254986, 2018). "Earlier reports of the potential prognosis effect of KIF4A in breast cancer and lung cancer were confirmed in present study using TCGA cancer cohorts." (PMID 28646197, 2017). "Abnormal expression of KIF4A induced apoptosis in breast cancer and metastatic invasion in lung cancer." (PMID 28562334, 2017). "Up-regulated genes, such as COL10A1, MMP11, NEK2, PAFAH1B3, KIF4A are highly related to breast cancer." (PMID 28245581, 2017). "Additionally, we demonstrated that there is an interaction between ERCC6L and KIF4A, both of which are closely related factors in mitosis and are involved in the malignant progression of breast cancer." (PMID 37667329, 2023). "MiR‐379‐5p inhibits the proliferation, migration and invasion of breast cancer by targeting KIF4A." (PMID 35608059, 2022). "KIF4A overexpression might promote lung cancer resistance to cisplatin, while in breast cancer cells, its overexpression promotes cell apoptosis during treatment with doxorubicin." (PMID 34055488, 2021). "In addition, 5 hub genes, CCNB2, FBXO5, KIF4A, MCM10, and TPX2 were identified and validated to be associated with the progression and worse prognosis of breast cancer." (PMID 30254986, 2018). "Moreover, ERCC6L and KIF4A may synergistically promote breast cancer cell proliferation, migration and invasion." (PMID 37667329, 2023). "For instance, miR-335, miR-379-5p, and miR-223-3p suppress KIF4A expression by targeting its 3’ untranslated region (3’-UTR), exerting tumor-suppressive effects in cancers like breast cancer." (PMID 41361459, 2025). "For validation in UALCAN, GEPIA, and KM, 5 core genes (KIF4A, RACGAP1, CKS2, SHCBP1, and HMMR) were found to highly expressed in breast cancer tissues with poor prognosis." (PMID 33959662, 2021). "Ectopic expression of KIF20A promoted chemoresistance of CRC cells to oxaliplatin or 5-FU treatment by decreasing apoptosis 37 and also indicated that expression of KIF4A, KIF15, KIF20A and KIF23 was correlated with prognosis in breast cancer." (PMID 33995648, 2021). "Elevated expression levels of kinesins KIF14, KIF4A, KIF20A, and KIF23, KIF2C, and KIFC1 have been reported in breast cancer cell lines, other kinesins KIF10, KIF18A, and KIF15 have been linked to prognostic indicators in breast cancer patients." (PMID 32346924, 2020). "We found that KIF23, KIF20A, KIF4A, KIFC1 and PRC1 were expressed at high levels in all investigated breast cancer cell lines." (PMID 28061449, 2017). "We confirmed that the expression of KIF4A, UBE2C and COL11A1 was distinctly increased in BC specimens compared with normal breast specimens, while the expression of SFRP1, SAA1 and RBP4 was distinctly decreased in breast cancer specimens." (PMID 35646102, 2022). "First, although high expressions of KIF4A, RACGAP1, CKS2, SHCBP1, and HMMR were independent prognostic factors of poor OS of breast cancer, all the data in our research came from online database and we need further experiments in vitro and in vivo to validate our findings." (PMID 33959662, 2021). "These five genes (KIF4A, RACGAP1, CKS2, SHCBP1, and HMMR) could be potential targets for therapy in breast cancer and prediction of prognosis on the basis of bioinformatical analysis." (PMID 33959662, 2021). "CKS2, KIF4A, RACGAP1, and SHCBP1 all have positive correlation with HMMR; they may become combined indicator of prognosis or targets for different subtypes of breast cancer." (PMID 33959662, 2021).
breast carcinoma (continued). "Additionally, study found that 26 of 38 kinesins detected in breast cancer MCF-7 cells are regulated by estrogen 17β-estradiol (E2) and many of them are upregulated by E2, including KIF15, KIF4A, KIF20A, and KIF23." (PMID 31729978, 2019). "Interestingly, the analysis of breast cancer datasets revealed that the expression of PICH correlates with that of mitosis-related genes, such as KIF4A, CEP55, MKI67, MELK, BUB1, CENPA, and AURKB." (PMID 31160555, 2019). "A study on breast cancer established that ATAD2 could be recruited to the KIF4A promoter region by estrogen receptors alpha (ERα) and other transcription factors to increase the transcription of KIF4A." (PMID 36046597, 2022).
lung carcinoma (30 papers, 2012 to 2025). "A large number of studies have confirmed that KIF4A is overexpressed in colorectal cancer, liver cancer, and lung cancer and is an independent prognostic risk factor." (PMID 34712733, 2021). "KIF4A has also been implicated in lung cancer response to chemotherapy." (PMID 40002279, 2025). "Kinesin family member 4A (KIF4A) is associated with poor prognosis in lung cancer and glioma." (PMID 38067227, 2023). "Interestingly, stable knockdown of PHF14 in lung cancer cells seems to cause a downregulation of KIF4A, which may indicate an intrinsic functional regulation between the two proteins." (PMID 28160558, 2017). "By forming a functional complex with PHF14, KIF4A synergistically facilitates lung cancer cell proliferation." (PMID 41361459, 2025). "In lung cancer, KIF4A plays a pivotal role in tumour progression and drug resistance by regulating various signalling pathways and mediating drug efflux." (PMID 41361459, 2025). "As a result, we demonstrated that KIF4A affected lung cancer stem cells (LCSCs) and glioma stem cells (GSCs) and regulated CSC signaling mechanisms." (PMID 38067227, 2023). "In conclusion, our study highlights the critical role of KIF4A in promoting cancer stem cells and epithelial-to-mesenchymal transition, contributing to the aggressiveness and metastatic potential of lung cancer and glioma." (PMID 38067227, 2023). "Our findings demonstrate a significant reduction in PAI-1 secretion upon suppression of KIF4A expression in lung cancer and glioma cells." (PMID 38067227, 2023). "As a result, we observed that KIF4A overexpression also enhanced the expression of CSCs markers in this lung cancer cell line." (PMID 38067227, 2023). "In this study, we investigated the role of KIF4A in lung cancer and glioma, focusing on its involvement in CSC and EMT, which play critical roles in tumor progression, metastasis, and treatment resistance." (PMID 38067227, 2023). "We first demonstrated that KIF4A is highly expressed in malignant lung cancer cells and that its expression correlates with poor prognosis in lung cancer patients." (PMID 38067227, 2023). "In this study, we investigated the involvement of KIF4A in cancer stem cells (CSCs) of lung cancer and glioma, and the relationship between KIF4A and cytokine PAI-1." (PMID 38067227, 2023). "By exploring the molecular mechanisms of KIF4A in lung cancer stem cells and glioma stem cells, we aim to provide a comprehensive understanding of its role in these malignancies." (PMID 38067227, 2023). "We found that overexpression of KIF4A in CSCs of lung cancer and glioma mediates tumor progression, invasion, and radiotherapy resistance." (PMID 38067227, 2023). "Previous studies have demonstrated the crucial role of KIF4A in the prognosis of several carcinomas, including colorectal cancer, cervical cancer, oral cancer, and lung cancer." (PMID 35126643, 2022). "KIF4A is closely related to prostate cancer, liver cancer, and lung cancer through the regulation of spindle formation, centrosome assembly, chromosome concentration and separation, and DNA damage repair." (PMID 35681641, 2022). "A number of KIFs show aberrant overexpression in various cancer cells, such as KIF4A, which is upregulated in cervical cancer and lung cancer, inhibits the repair of damaged DNA double-strand in lung cancer cells sensitive to cisplatin." (PMID 35812733, 2022). "The present study identified and validated NUF2, KIF4A, KIF18B, DLGAP5, NEK2, and LRRK2 as promising diagnostic biomarkers for lung cancer." (PMID 36499051, 2022).
lung carcinoma (continued). "We noted that the expression patterns of PHF14 and KIF4A in these lung cancer samples are quite the same." (PMID 28160558, 2017). "Here, we found that PHF14 was co-overexpressed with KIF4A in lung cancers and the two proteins formed a functional complex involved in cell mitosis and tumorigenesis." (PMID 28160558, 2017). "KIF4A, a potential marker for lung cancer, is detected by mass spectrometry with high abundance (unpublished data)." (PMID 28160558, 2017). "KIF4A has been reported to be a potential marker in lung cancer and to play critical roles in multiple aspects of mitotic and chromatin regulation." (PMID 28160558, 2017). "Kinesin family member 4A (KIF4A), a microtubule-binding motor protein, is a candidate oncogene identified in lung cancer." (PMID 25587357, 2014). "KIF4A was overexpressed in cervical and lung cancers, whereas KIF4A was down-regulated in gastric cancers." (PMID 24386490, 2013). "Collectively, they indicate KIF4A’s therapeutic potential in lung cancer and rationalize the development of KIF4A-targeted inhibitors that could be dually effective by antagonizing its transport and mitotic functions." (PMID 40002279, 2025). "Additionally, KIF4A has notable pan-cancer traits, being overexpressed and linked to poor prognosis in numerous malignancies like endometrial, prostate, glioma, hepatocellular, colorectal, breast, and lung cancers, meaning targeting strategies could benefit a wide range of cancer patients." (PMID 41361459, 2025). "KIF4A knockdown suppresses tumor progression and promotes chemosensitivity in lung cancer." (PMID 38937742, 2024). "Furthermore, we found out that KIF4A is a key regulator of PAI-1 which is secreted from lung cancer and glioma." (PMID 38067227, 2023). "KIF4A is a gene that we identified in ALDH1+ lung cancer cells and CD133+ glioma cells." (PMID 38067227, 2023). "It is possible that KRAS might regulate KIF4A in a cell type-specific manner, and this particular regulation in the context of lung cancer requires further elucidation." (PMID 36499051, 2022). "PLK1, EPHK10, and KIF4A also play important roles as prognostic indicators or as targeted therapy sites for the progression of multiple tumors, such as pancreatic cancer, esophageal squamous cell carcinoma, bladder cancer, and lung cancer." (PMID 35495629, 2022). "In cases of lung cancer, KIF4A was reported to promote cell proliferation and migration and inhibit apoptosis in LUAD cell lines, whereas KIF18B was suggested to promote LUAD cell proliferation, migration, and invasion via the Rac1/Akt/mammalian target of rapamycin (mTOR) signaling pathway." (PMID 36499051, 2022). "KIF4A was also reported to be significantly increased in lung cancer and cervical cancer." (PMID 30872592, 2019). "And similar to PHF14, KIF4A has been related to poor prognosis in lung cancers." (PMID 28160558, 2017). "In lung cancer, the KIF4A gene was observed to be highly transactivated." (PMID 23320178, 2012). "Moreover, the inhibition of KIF4A suppresses cell growth in lung cancer." (PMID 30744636, 2019). "We confirmed that three kinesin genes (KIF4A, KIF20A, and KIF11) have some influence on the occurrence and progression of lung cancer." (PMID 41462522, 2025). "In lung cancer, it promotes tumour progression through the PI3K/AKT pathway, resulting in increased expression of p21; silencing KIF4A leads to upregulation of p21 and heightened sensitivity to doxorubicin." (PMID 41361459, 2025). "Here, NUF2, KIF4A, and KIF18B were commonly upregulated, and LRRK2 was commonly downregulated in both lung cancer subtypes." (PMID 36499051, 2022). "For the first time, we propose NUF2, KIF4A, KIF18B, DLGAP5, NEK2, and LRRK2 as biomarkers for lung cancer progression." (PMID 36499051, 2022).